IFNG (interferon gamma)
Diseases named in the same sentence as IFNG in open-access papers (continued):
Sharing a sentence is not in itself a finding about the gene and the disease.
tumor (continued). "Despite these T-cell changes, there were no corresponding differences in before- and after-treatment responses to shared tumour antigens such as MAGE-A4 in terms of interferon gamma response." (PMID 37958391, 2023). "Considering the increasing recognition of the dual role played by IFNγ in tumour development, it will be necessary to gain a more comprehensive understanding of the effects of IFNγ in the future." (PMID 37056922, 2023). "Macrophages M1 induced by interferon-gamma and LPS can kill tumour cells and pathogens, whereas macrophages M2 induced by IL-4, IL-10, and IL-13 exhibit anti-inflammatory activity and contribute to tumour invasion and angiogenesis." (PMID 37370746, 2023). "Our results indicate that Adam2-mediated reduction of IFNγ signaling facilitates tumor growth primarily through downregulation of pathways associated with antigen presentation and overall activation of endogenous antitumor T-cell responses." (PMID 37258521, 2023). "Expanded T cells were co-cultured with autologous PDTOs for two weeks, then restimulated for analysis for tumor reactivity by IFNγ production and tumor killing by cleaved caspase-3 production in tumor organoids." (PMID 37790365, 2023). "We observed that anti-IFNγ antibodies administered two days after the first injection of cisplatin can promote tumour chemotherapy." (PMID 37056922, 2023). "Low-dose chemotherapeutic drugs initially inhibited TβRI expression on tumor cells but promoted IFNγ secretion and T-cell infiltration into tumors." (PMID 37190141, 2023). "In contrast, stimulation with the IR HNSCC tumor antigen resulted in attenuated levels of IFNγ production." (PMID 37444444, 2023). "IFNG is a cytokine that regulates immune processes and has antimicrobial and anticancer activities, e.g., it induces iron death in tumor cells and inhibits tumor growth." (PMID 38146369, 2023). "In the equilibrium phase, the immune system (mainly T helper type 1 (Th1) cells, cytotoxic T cells, and cytokines of type 1 immunity (IL12, IL2, interferon gamma (IFN-γ)) keeps tumor cells dormant or growing slowly." (PMID 37445860, 2023). "IL-12 has been considered a strong candidate for cytokine-based immunotherapy due to its potent properties in promoting anti-tumour type 1 immunity and IFNγ responses." (PMID 37455828, 2023). "Overall, NHS-IL12-mediated tumor suppression in murine hosts is intrinsically related to IFNγ levels in a dose and tumor model-dependent manner." (PMID 38260854, 2023). "Based on these observations, it is recommended to prioritise PARP14i for clinical trials in cancer patients progressing on ICBT, especially when increased IFNγ signalling is detected in the tumour or plasma." (PMID 37752135, 2023). "In our study, MHC-I/HLAA-C was upregulated following IFNγ treatment in tumor cells of varying basal MHC-I/HLAA-C expression." (PMID 37582744, 2023). "The selective inhibition of IDO2 will be of particular interest, as it promotes expression of IFNγ and increases effector cell invasion of the tumor microenvironment, suppressing growth and cell migration." (PMID 37296860, 2023). "In this study, we demonstrated that the delivery of anti-IFNγ antibody to the capillary leaky site prevented cisplatin-induced vascular damage, thereby promoting drug delivery and improving tumour chemotherapy." (PMID 37056922, 2023). "Conversely, Hh-deficient CD4+ T-cells adopt Th-1 phenotype, which produces interferon-gamma (IFN-γ) and evokes CD8+ T cell activation and tumor suppression." (PMID 37213270, 2023). "IM can promote tumor growth in mice by regulating immune responses, such as increasing interferon gamma (IFN-γ)-producing T cells and decreasing interleukin 17a (IL-17a)- and IL-10-producing T cells." (PMID 37009513, 2023). "Our model predicted that CTL cytotoxicity played only a minor role in tumor control relative to the cytostatic effects of IFNG." (PMID 37182110, 2023).
tumor (continued). "Overall, peak levels of 14 serum markers after treatment correlated with tumor reduction, and serum IFNγ levels showed the largest positive correlation." (PMID 36624315, 2023). "Collectively, we conclude that the integrity of endothelial cells in tumours with chemotherapy is controlled by IFNγ-stimulated glycolysis." (PMID 37056922, 2023). "Another study found that IFNγ generated in the TME by activated T cells paired with arachidonic acid affected spontaneous antitumor immunity in vivo by inducing tumor cell ferroptosis through acyl-CoA synthetase long-chain family member 4 (ACSL4)." (PMID 37213276, 2023). "CREKA-lipo-anti-IFNγ combined with cisplatin reduces tumour weight compared with that in control group mice, whereas lactate abrogates the effect of CREKA-lipo-anti-IFNγ." (PMID 37056922, 2023). "IFNγ and TNFα can stimulate or activate other anti-tumor immune responses (both adaptive and innate) and can promote antigen presentation, which supports tumor recognition and elimination." (PMID 36175673, 2023). "RT-generated IFNγ production within the primary tumor facilitates cytotoxic T-cell trafficking, adhesion to the endothelium, and diapedesis." (PMID 38276666, 2023). "The presence of intratumoral heterogeneity makes it plausible that a subset of tumor cells is resistant to the antitumorigenic effects of IFNγ, yet is sensitive to other IFNγ-driven responses, including partial or full EMT." (PMID 37638024, 2023). "With this mitochondria-targeted polyplex, they demonstrated the ability to induce immunotherapy by increasing interferon-gamma (IFN-γ) in tumor cells." (PMID 36839894, 2023). "Further digging into the genes regulated by the IFNγ pathway is not only of great significance for the basic research of tumor immunity but also important for the treatment of clinical patients." (PMID 37427373, 2023). "CAR-T cells have direct anti-tumor activity against antigen-positive tumor cells by releasing perforin, granzyme, and Interferon-gamma (IFN-γ)." (PMID 37371075, 2023). "Preclinical and small cohort studies suggest gastrointestinal microbiome composition and exosomal mRNA expression of PD-L1 and IFNγ from the primary tumor, stool and body fluids as potential biomarkers for response." (PMID 37509655, 2023). "To determine the function of B cells in dLNs of tumor-bearing mice, we evaluated their ability to suppress IFNγ production of T cells in response to anti-CD3/CD28 stimulation in vitro." (PMID 37291146, 2023). "IFNγ itself is an effective tumor inhibitor, inducing the surface expression of PD-L1, thereby contributing to cancer cell cycle arrest and dormancy." (PMID 37296860, 2023). "STAT3 inhibitor (stattic) reversed PDL1/2 induction but maintained IFNγ-mediated anti-tumor responsiveness, underscoring that immune evasion can be alleviated." (PMID 37686465, 2023). "In our study, combined with proven immunotherapy predictive markers, COAD of the high autophagy score group or high IFNG group tended to be “hot tumor” tissues and were more suitable for immune checkpoint inhibitor therapy." (PMID 36756126, 2023). "The JAK-STAT pathway, which regulates the expression of MHC class I and PD-L1 in tumor cells, is activated by the release of IFNγ from effector T cells." (PMID 37038154, 2023). "Within these dynamic effects of hexatherapy, N803 contributed to the increased proliferation and decreased exhaustion of CD8+ T cells in the TME, as well as the enhanced transcription of tumor IFNγ and T-cell-attracting chemokines." (PMID 37371081, 2023). "CXCL9 is induced in antigen presenting cells in response to IFNγ, which amplified engraftment of tumor infiltrating lymphocytes and helped establish the ‘‘hot’’ tumor immunophenotype." (PMID 37365574, 2023). "NAMPT is clearly important for cell homeostasis, and we have identified a novel IFNγ-induced mechanism by which NAMPT enhances tumor burden." (PMID 36900204, 2023).
tumor (continued). "De-differentiation was driven by a sustained tumor-intrinsic IFNγ signaling program in 5/11 de-differentiated PD1 PROGs." (PMID 36934113, 2023). "We additionally examined 24 cell-type specific gene expression signatures included in the NanoString immune panel as well as an IFNγ signature for characterizing immune cell subsets within the tumor microenvironment." (PMID 37883360, 2023). "Decrease in DNAM-1 limits NK cytotoxicity and blocks IFNγ production, while the overexpression of DNAM-1 ligand in tumor cells causes a decrease in NKG2D ligands, indicating that NK cell-induced killing is initiated by DNAM-1 or NKG2D signaling pathway." (PMID 37190251, 2023). "Defective TLR1 on DCs impaired their maturation ability by HMGB1 and reduced the secretion of IFNγ from T cells to eradicate tumor cells in vitro." (PMID 37945630, 2023). "Recent studies have shown IFNγ has a profound effect on tumor signaling and can act as an inducer of ICI resistance." (PMID 38130991, 2023). "We also treated these cells with interferon-γ (IFNγ) to simulate a tumour microenvironment with an active immune response." (PMID 37582853, 2023). "Immune cells such as CD8+ T cells have the ability to sensitize tumor cell ferroptosis through secretion of IFNγ, which reprograms the metabolism of amino acid or fatty acid in tumor cells." (PMID 37553341, 2023). "The tumors showed reduced CD8 T cell infiltration (CD8 TILs) and lower IFNγ in the recTLT-1–injected mice, supporting increased tumor growth and compromised antitumor response by CD8 T cells in these mice." (PMID 36305874, 2023). "Areas enriched for CD8+ T cells and IFNγ are related to the juxtaposition of lymphoid and tumor cells within the TME, which results in high clustering of enhanced NOS2-expressing cells." (PMID 37169743, 2023). "In more detail, tumors with an inflamed phenotype, characterized by high T-cell infiltration, increased interferon gamma (IFN-γ) signaling, expression of programmed death-ligand 1 (PD-L1), and high tumor mutational burden, tend to be more responsive to ICIs." (PMID 37176042, 2023). "Significant associations were observed between stromal, immune, ESTIMATE scores, tumor purity and IFNG expression." (PMID 36756126, 2023). "This indicates that both hematopoietic and non-hematopoietic cells can respond to IFNγ to control tumors, suggesting a highly compensatory, multimodal mechanism of tumor control during equilibrium in which IFNγ is a key node." (PMID 36881506, 2023). "In their analysis of biomarker data, a high tumor mutational burden (TMB) and high interferon-gamma (IFN-γ)-related gene expression score was associated with improved pathologic response and reduced recurrence." (PMID 37444454, 2023). "Further assessment of frequencies and relative levels of other effector T cell populations in tumor versus STM showed a notable shift in the ratio of IFNγ+ to IL-17A+ T cell frequencies (on both CD4+ and CD8+ T cell subsets)." (PMID 38074634, 2023). "This interpretation is consistent with higher gene expression of effector- and division-associated genes (GZMB, IFNG, MKI67) in the untreated tumor and low expression of activation markers such as HLA-DR and CD38 in the irradiated tumor." (PMID 37209684, 2023). "Among 232 ARGs, IFNG was generally significantly correlated with tumor immunotherapy biomarkers (PD-L1, CD8A and cytotoxic T lymphocytes (CTL))." (PMID 36756126, 2023). "In contrast, IFNγ pre-treatment eliminated the ability of tumours to respond to α-PD-1 therapy significantly shortening survival, indicating that adaptation to IFNγ promotes α-PD-1 therapy resistance." (PMID 37752135, 2023). "Specifically, IFNγ released from CAR-T cells was shown to remodel the tumor immune landscape and promote a more activated and less suppressive tumor microenvironment." (PMID 38052854, 2023). "Mice receiving either 0 or 50 μg of anti-IFNγ had similar tumor growth curves with 5 of 8 mice eliminating tumor in each group." (PMID 38130991, 2023).
tumor (continued). "We made similar observations for Stat1 and other STAT1 target genes including Irf1, Cxcl10, and Cxcl11, which suggested that PARP14 was induced specifically in IFNγ-inflamed tumours but independently of α-PD-1." (PMID 37752135, 2023). "It has been shown that the secretion of IFNγ by tumor-infiltrating T cells results in the overexpression of PD-L1 in tumor cells, allowing cancer to escape from the immune system’s response." (PMID 36982608, 2023). "As a case in point, tumor cells often upregulate the immune checkpoint protein Programmed Death-Ligand 1 (PD-L1), either in response to inflammatory cytokines, such as Interferon gamma (IFNγ), or through constitutive oncogenic signaling." (PMID 37638024, 2023). "This cancer vaccine and tumor-directed IFNγ treatment enhanced T-cell infiltration and T-cell-mediated tumor control." (PMID 38006049, 2023). "The detection of cytosolic DNA by PRRs initiates IFNγ signaling and accompanying innate and adaptive immune responses, similarly as in the case of DAMPs, facilitating the anti-tumor immune response." (PMID 36831197, 2023). "Ptpn2-mediated dephosphorylation of Stat1 and Jak1 negatively regulates signaling induced by IFNγ, a potent inhibitor of tumor growth via stimulation of the antitumor immune response." (PMID 36968224, 2023). "This is indicating an influence of the accumulation of the CD48-positive tumor cells in the tumors on the cytotoxic effects mediated by IFNγ stressing the importance of the in vivo study to evaluate the efficiency of the treatment." (PMID 37609636, 2023). "TNFα is reported to synergize with IFNγ to induce Jak1/Stat1-dependent tumor cell death and recruit cytolytic T cells to the tumor microenvironment." (PMID 36968224, 2023). "Together, CD4+ T cells and IFN-activated mononuclear phagocytes initiate an indirect inflammatory tumour cell death process that acts from the ‘outside-in’ and can be abrogated by neutralizing IFNγ." (PMID 37316667, 2023). "Mice treated with partial tumor volume irradiation induced a robust IFNγ and Th1 response when compared to whole-tumor irradiation and down-modulated TH2 functions." (PMID 37979032, 2023). "For instance; the IFNγ-mediated anti-tumor role is well described, however, recent observation from preclinical studies questioned such role." (PMID 37816781, 2023). "The model also features CTLs, which kill tumor cells at rate ke and produce IFNG, which precludes tumor cells from transferring from G1 phase to S phase." (PMID 37182110, 2023). "Intrinsically, NK cells require secretion of interferon gamma (IFNγ), tumor necrosis factor alpha (TNFα) and granzyme B for anti-tumor response." (PMID 38193082, 2023). "Here, we provide evidence that IFNγ directly acts on intra-tumoral CD8 T cells to restrict anti-tumor responses." (PMID 36658158, 2023). "For instance, CD8(+)T cells released interferon gamma to inhibit glutamate-cystine antiporter system xc-, enhance lipid peroxidation and to promote ferroptosis in tumor cells." (PMID 37589000, 2023). "Our results provide a basis for improving tumour chemotherapy through tissue-specific IFNγ blockade." (PMID 37056922, 2023). "In the cancer setting, extracellular ISG15 acts as an immune adjuvant to enhance antigen specific CD8+ T cell tumor immunity, increasing their production of IFNγ." (PMID 36911698, 2023). "The study is first prospective study that simultaneously determines the expression of IFNγ and PD-L1 in tumor tissue and blood at different time points." (PMID 37509655, 2023). "Tumor-targeted IL12 products typically led to a significant elevation of IFNγ levels, both in the tumor and in the blood." (PMID 36839699, 2023). "IFNγ, produced mainly by activated T lymphocytes and natural killer cells, promotes macrophage activation, infiltration into tumor tissues and inhibition of differentiation into TAMs." (PMID 37346794, 2023).
tumor (continued). "(C, D) Splenocytes from tumor-bearing mice were used in an IFNγ ELISpot to determine the frequency of NeoAg-specific T cells in the periphery at days 7, 10, and 14 after tumor implantation." (PMID 37548358, 2023). "First, we measured the ability of the REP TILs to produce the cytokines IFNγ and TNFα when cocultured with the tumor cells." (PMID 37484198, 2023). "The importance of the IFNγ pathway was confirmed by generating IFNγR1 KO glioblastoma cells which were more resistant to CAR T cell-mediated killing than wild-type tumor cells." (PMID 36189315, 2022). "This improvement was associated with an increase in Tcytotoxic, IFNγ+ Tcytotoxic cells, and the ratio of these cells to Tregulatory and MDSC in the tumours of the animals treated with pHIFU and ICI compared to the control animals." (PMID 35158903, 2022). "IL-10 produced by MDSCs induce increased expression of lymphocyte activation gene 3 (LAG3) and the consequent decreased IL-2, IL-12, and IFNγ secretion by T cells, which hampered their proliferation and anti-tumor activity." (PMID 35757002, 2022). "Diphtheria toxin administered to deplete Tregs showed an enhanced tumor rejection in mice with liver metastases and an increase in the expression of IFNγ, ICOS and CD107a on CD8+ T cells." (PMID 36466910, 2022). "Using IL-2, adenoviral gene therapy in prostate cancer patiets was welltolerated; inducing tumor lymphocytic infiltration, increase in IFNγ and IL-4secretion within the tumor, and decrease in prostate specific antigen (PSA)levels." (PMID 36206378, 2022). "Excitingly, incomplete inhibition of the C11BM complex either by reducing CARD11 expression or by pharmacological inhibition of MALT1 prevents lethal autoimmune reactions, but converts tumor-infiltrating Treg cells into IFNγ-secreting effector T cells." (PMID 35203553, 2022). "We demonstrated that DuoBody-CD3x5T4 can induce bystander killing of 5T4− tumor cells, which (at least in part) depends on the presence of activated T cells and soluble factors produced by these cells, including IFNγ." (PMID 36271507, 2022). "Although both combinations showed tumor growth inhibition, cabozantinib/nivolumab had enhanced cytotoxic IFNγ and TNFα+ T cells." (PMID 36419897, 2022). "Obvious differential activities of some ligands between tumor cell states were observed when tumor cells act as receivers, such as intermediate tumor cells that received the strongest ligand IFNG signal compared to other tumor cell states." (PMID 35903095, 2022). "Radiation can be a double-edged sword in its impact on the immune system and can cause immunosuppression through the increased expression of regulatory T cells and the upregulation of PD-L1 on tumor cells through the production of interferon-gamma (IFN-γ)." (PMID 36551787, 2022). "Overall, this suggests that IFNγ produced by NK cells increases HRL expression on CD31+ tumor vasculature and promotes T cell infiltration in early-stage tumors." (PMID 36531040, 2022). "Experimental evidence has already shown that interferon gamma (IFN-γ) released by CD8+ T cells promotes tumor cell ferroptosis." (PMID 35795206, 2022). "Combinatorial pre-activation generates “cytokine-induced memory-like (CIML)” NK cells, which have displayed higher IFNγ production, proliferation, and anti-tumor effects, and share these properties with NKG2C+ memory-like NK cells." (PMID 36231109, 2022). "On the other hand, IFNγ induces many signals in T cells to efficiently enable T cell function, while the inhibition of IFNγ signaling pathways in T cells reduces T cell responses and permits tumor growth and persistence." (PMID 35606804, 2022). "ELISA showed higher expressions of Tnfα and Ifnγ in the tumor lysates of the Foxf2-expressing group, indicating an enhanced T-cell activity." (PMID 36369237, 2022). "It was found that such desired effects were likely related to the activation of CD8 + T cells and APCs in tumor tissue and also enhanced systemic IFNγ levels." (PMID 34980128, 2022).